MCM6 (minichromosome maintenance complex component 6)
Diseases named in the same sentence as MCM6 in open-access papers (continued):
Sharing a sentence is not in itself a finding about the gene and the disease.
periodontitis (1 paper, 2024). An acute or chronic inflammatory process that affects the tissues that surround and support the teeth. "Notably, four of these high-confidence genes were found to be involved with multiple phenotypes: S100A9, S100A12 (neutrophils and periodontitis); MCM6, P14KAP2 (neutrophils and pDC)." (PMID 38536078, 2024).
Primary microcephaly (1 paper, 2023). Head circumference below 2 standard deviations below the mean for age and gender at birth. "These two individuals presented with severe growth delays and primary microcephaly, suggesting that the MCM6 zinc finger domain is crucial for cell proliferation." (PMID 37198333, 2023).
prostate adenocarcinoma (1 paper, 2025). "It was determined that 21 proteins (DHX9, EIF5, HPRT1, INPP5B, MCM6, PPP6C, SYF2, etc.)whose expression was increased in PC3‐R cells based on label‐free nLC‐MS/MS analysis were consistent with both TCGA prostate adenocarcinoma N0 and N1 nodal metastasis status and correlation data." (PMID 39799471, 2025).
retinoblastoma (1 paper, 2025). A malignant tumor that originates in the nuclear layer of the retina. "In retinoblastoma, hypermethylation of MCM6 leads to reduced expression, which can disrupt normal DNA replication control and contribute to tumorigenesis by affecting cell cycle regulation." (PMID 41150792, 2025).
serous ovarian cancer (1 paper, 2021). "The serous ovarian cancer dataset indicated that the percentages of DNA alterations of MCMs were 5% (MCM2), 4% (MCM3), 5% (MCM4), 2.6% (MCM5), 1.2% (MCM6), and 5% (MCM7)." (PMID 34178669, 2021).
silicosis (1 paper, 2023). Silicosis is a respiratory disease caused by breathing in (inhaling) silica dust. "In the rat model exposed to silica inhalation for 4 weeks, Bub1, Kifc1, Mcm6, and Prc1 were upregulated in the silicosis group, while Cdkn3 was downregulated." (PMID 37278873, 2023).
type-2 diabetes (1 paper, 2024). "The aim of this reported study was to analyse the relationship between the rs4988235 variant of the MCM6 gene and bone mineral density and the risk of type-2 diabetes in women after menopause." (PMID 39275317, 2024). "An analysis of these data in combination with the prevalence of the G allele showed that the GG homozygote women with rs4988235 polymorphism of the MCM6 gene were significantly more likely to have type-2 diabetes relative to the A allele carriers (p = 0.023)." (PMID 39275317, 2024). "No follow-up analysis was carried out to better assess the effect of the rs4988235 genotype of the MCM6 gene as a risk factor on the development of complications in type-2 diabetes or the incidence of fractures in the women studied, especially those with reduced bone mineral density." (PMID 39275317, 2024).
cancer (53 papers, 2010 to 2025). A tumor composed of atypical neoplastic, often pleomorphic cells that invade other tissues. "Deletion and post‐translational modifications (PTMs) of MCM6 are associated with human diseases, particularly in cancer, also as profound impacts on therapy resistance." (PMID 39477811, 2025). "For example, MCM6 is involved in DNA replication and has been linked to cancer and inflammatory responses." (PMID 40362323, 2025). "These genes, including Smc2, Mcm3, Ccnd1, Rasal2, Mcm6, and Mad2l1, are linked to cancer progression and metabolic regulation." (PMID 39272991, 2024). "Of interest, many of the identified candidate proteins belong to protein families that already have cancer‐associated members (such as MCM6 and MCM7 proteins, MAPK8, or CDC7)." (PMID 29572294, 2018). "Similarly, MCM proteins, which are essential for DNA replication licensing and serve as emerging proliferation markers, were significantly associated with C1GALT1 expression—most notably MCM4 and MCM6, which were consistently correlated across cancers." (PMID 40548474, 2025). "Following this, we utilized canSAR.ai and DISGENET Plus to evaluate the relationship between elevated MCM6 expression and various cancers and diseases." (PMID 39477811, 2025). "Alongside with other MCM subunits, MCM6 collaborates to facilitate the unwinding process and ensure accurate genome replication, as a significant marker of multiple cancer types." (PMID 39477811, 2025). "MCM6 expression has been studied in various human cancers, including clear cell renal cell carcinoma." (PMID 40445576, 2025). "MCM6 emerged as a common responder to DiPRO1 downregulation in both myoblasts and mesenchymal cancer cells, providing further evidence of DiPRO1 shared role in cell proliferation." (PMID 39009887, 2024). "The expression levels of E6AP and MCM6 in cancer tissues were both higher than those in adjacent tissues." (PMID 37454373, 2023). "Overexpression of MCM6 is found in many human cancers, and knocking down it significantly inhibits cell proliferation." (PMID 37407632, 2023). "The fact that YAP confers therapy resistance in various cancer types prompted us to investigate the effect of knocking down MCM6, a critical transcriptional target of YAP in GC, on the sensitivity of GC to chemotherapy." (PMID 36185598, 2022). "MCM6 is found to be overexpressed in several cancer types, including gastrointestinal cancers 9-12, breast cancer 13, neuroblastoma 14, and mantle cell lymphoma 15, and contributes to cancer development." (PMID 36185598, 2022). "As such, MCM6 depletion together with DNA-damaging agents exacerbated the accumulation of damaged DNA, which further led to massive cancer cell death and tumor regression." (PMID 36185598, 2022). "Pathway analysis based on the database for Kyoto Encyclopedia of Genes and Genomes (KEGG) identified several cancer-related pathways that were regulated by MCM6, of which PI3K/Akt and focal adhesion signaling appeared top-ranking." (PMID 36185598, 2022). "Some BIIGs were upregulated in multiple cancer types: Top2a, Mki67, Rrm2, Mcm6, and Spp1 were upregulated in more than eight cancer types, while Emp1, Ptx3, and Socs3 were upregulated in seven cancer types." (PMID 36605216, 2022). "To conclude, the present study provides evidence eliciting that overexpression of LINC00472 can suppress cancer progression and metastasis via down-regulation of MCM6 in TNBC." (PMID 33668040, 2021). "Gene amplification and overexpression of MCM6 are found in many human cancers, which correlates with tumor genesis and progress, as well as aggressive biological behaviors." (PMID 34233647, 2021). "Several studies demonstrated overexpression of MCM6 also predicts poor survival in patients with several types of cancer, including HCC." (PMID 32082966, 2019).
cancer (continued). "Additionally, data from canSAR.ai indicated that MCM6 expression correlated with the pathological stages of most cancers." (PMID 39477811, 2025). "The literature has demonstrated overexpression of MCM2, MCM4, and MCM6 in various cancers." (PMID 40445576, 2025). "In many cancer cells, MCM6 expression is enhanced and can be used as a therapeutic target." (PMID 37880682, 2023). "It has been demonstrated that MCM6 has cancer-promoting effects in HCC." (PMID 36263426, 2022). "The utility of Protocol 1 was confirmed by the revealed upregulation of cancer-associated MCM6 in HaCaT keratinocytes induced by non-toxic concentration of SDS." (PMID 36509991, 2022). "High expression of MCM6 was found in 49 cancer datasets compared to that in normal tissue datasets." (PMID 34178669, 2021). "More recently, a study documented a high expression of MCM6 in TNBC, but whether MCM6 can affect cancer progression and metastasis in this malignancy is uncertain." (PMID 33668040, 2021). "MCM2-7 were all upregulated in carcinoma tissue in our data, and MCM3, MCM4, and MCM6 were associated with differential miRNA expression, including hsa-miR-106b-5p, hsa-miR-17-5p, hsa-miR-19b-3p, hsa-miR-20a-5p, hsa-miR-20b-5p, hsa-miR-25-3p, and hsa-miR-93-5p." (PMID 29725503, 2018). "Hence, missense SNPs in MCM6 might alter DNA replication and cell proliferation by interacting with other 20 genes and resulting in serious health hazards even cancer." (PMID 38773180, 2024). "Remarkably, the group of cancer-related proteins,i.e., CEACAM1,CEACAM5, and CEACAM6 as well as the minichromosome maintenance complexcomponents MCM3, MCM4, and MCM6 showed clear protein abundance patternsrelated to the radiation response." (PMID 40574313, 2025). "MCM6, MCM7, and MCM8 collaborate with other MCM family members to promote cancer cell proliferation through cell cycle and DNA replication." (PMID 35360518, 2022). "We observe that the mini-chromosome maintenance proteins (MCMs) MCM2, MCM3, MCM6 and MCM7, which were upregulated in most of the cancers, also regulate the expression of a significant number of high centrality genes in the network." (PMID 34728699, 2021). "b); and the CNVs (deletion) and expression of MCM6 and CENPH, which enhanced cancer cell proliferation, stemness, and metastasis and promoted cancer development, were also increased with the increase of Gleason grade." (PMID 33985534, 2021). "In pathway in cancer and cell cycle, Bcl2, VEGFA, PTEN, Jun, Fos, APC2 were up-regulated and Ccna2, Cdc25a, Mcm3, Mcm6, Ccnb2, Mcm5, Cdk1, Gadd45a, Myc were down-regulated in the MMQ tumor stem-like cells." (PMID 28163656, 2017). "The discovery of genes such as MCM6 and RPS26, which are involved in these interactions, not only underscores the genetic susceptibility to microbiome‐related cancer pathways but also opens up possibilities for targeted therapies." (PMID 39906083, 2025). "Further investigation of the functions of MCM6‐Kcr in diverse cellular pathways will deepen our understanding of the complex PTM code and provide clues for future drug development to combat diseases, including cancer." (PMID 39477811, 2025). "Knock-out of TMCMPRSS4 could lead to down-regulation of MCM6 in NSCLC, which in turn leads to down-regulated proliferation and migration of cancer cells." (PMID 33936158, 2021). "MCM2 and MCM6 are the upstream transcription factors regulating the ORC1 protein factor and are upregulated in the case of cancer; therefore, it could provide some explanations for the upregulation of ORC1." (PMID 32193399, 2020).
cancer (continued). "In addition, CDC20, CDK4, MCM6, MAD2L1, MCM2 and MCM5 were leading genes intersecting in these four pathways, and a positive correlation between mRNA expression and LACTB was observed in most normal and cancer tissues." (PMID 33507917, 2021). "Further cell cycle analysis of cancer cells showed that zebularine inhibited tumor cell growth, mainly by suppressing cell cycle G1 phase and expression of cell proliferation-related genes Pcna; however, we did not see the consistent change in the mRNA expression of Mcm6 and Mki67 by zebularine." (PMID 38755254, 2024). "Furthermore, certain cell cycle–related proteins, including TOP2A, PCNA, MCM2, MCM4, MCM5, MCM6, and MCM7, have also been reported to facilitate cancer cell proliferation, and the enhanced expression of these cell cycle–related proteins may contribute to uncontrolled ESCC cell proliferation." (PMID 38652547, 2024). "Cancers arising in different anatomic sites are also associated with minichromosome maintenance complex component 2 (MCM2), MCM4, and minichromosome maintenance complex component 6 (MCM6) overexpression, but there is not much information about the role of MCM4 in PC." (PMID 36329790, 2023).
tumor (51 papers, 2013 to 2025). "High MCM6 expression is associated with tumor invasion and the development of metastasis via enhanced tumor cell proliferation rates." (PMID 37198333, 2023). "To investigate the discrepancy expression of MCM6 in tumour versus normal tissues, we analysed the physiological mRNA levels of MCM6 across various normal tissues using the GTEx data set." (PMID 39477811, 2025). "Numerous studies have indicated that dysregulation of the MCM6 complex is frequently observed in various tumours." (PMID 39477811, 2025). "Concurrently, kaempferol, which acts as a regulator of SIRT7, was found to enhance the Kcr level of MCM6, reducing tumour weight, particular when combined with paclitaxel, highlighting its potential chemotherapeutic target for BRCA therapy." (PMID 39477811, 2025). "MCM6 acts as a universal biomarker for tumour growth, owing to its critical roles in DNA replication and cell cycle regulation." (PMID 39477811, 2025). "Among the MCM members, the molecular mechanism of how missense SNPs of minichromosome maintenance complex component 6 (MCM6) contribute to DNA replication and tumor pathogenesis is underexplored and needs to be elucidated." (PMID 38773180, 2024). "The important role of MCM6 in cell proliferation has been reported, indicating its potential function in promoting tumor progression." (PMID 37454373, 2023). "Depletion of MCM6 abolished GC tumor growth and sensitized GC to standard cytotoxic treatments via suppression of the DNA damage-induced ataxia telangiectasia and rad3-related protein/checkpoint kinase 1 (ATR/Chk1) signaling." (PMID 36185598, 2022). "Skp2 modulation, and the loss of its substrates p27 and Mcm6, and the E2f family are clinical markers for a poor outcome in CRC, its malignancy, and CRC tumor growth." (PMID 35457963, 2022). "In our study, we observed comparable results for MCM6 and its meaningful correlations with tumor grade, hormone receptor status, and molecular subtypes." (PMID 35125121, 2022). "MCM6 expression is significantly higher in GC tumors compared with non-tumor tissues and predicts poor survival in GC patients in our study, which is same as YAP 7, alluding to the possibility that MCM6 plays an oncogenic role in GC." (PMID 36185598, 2022). "Using TCGA-STAD dataset, MCM6 mRNA levels were significantly upregulated in GC tumors (n = 415) as compared to adjacent non-tumor tissues (n = 35) (P < 0.001)." (PMID 36185598, 2022). "Consistently, higher MCM6 expression was found in both intestinal- and diffuse-type GC tissues compared to normal gastric tissues, particularly within the tumor area by IHC staining." (PMID 36185598, 2022). "When subdividing patients by TNM tumor stage, high MCM6 protein expression particularly predicted poor prognosis for patients with early (stage I and II) GC (P = 0.0076)." (PMID 36185598, 2022). "In line with in vitro findings, knockdown of MCM6 significantly inhibited tumor growth in vivo (P < 0.001)." (PMID 36185598, 2022). "Lastly, the in vivo effects of LINC00472/MCM6 on TNBC cell growth were explored by inoculating the stably transfected MDA-MB-231 cells into the right axilla of nude mice for tumor formation." (PMID 33668040, 2021). "The available evidence conferred that overexpressed LINC00472 leads to suppression of the TNBC cell oncogenic properties in vitro as well as inhibited tumor growth in vivo by down-regulating MCM6 and blocking the MEK/ERK signaling pathway." (PMID 33668040, 2021). "The expression of MCM6/9/10 was low in normal tissues, but medium and high protein expression was observed in tumor tissues." (PMID 34404366, 2021). "MCM2, MCM3, MCM6, MCM8, MCM9, and MCM10 groups significantly varied and associated with the tumor stages." (PMID 34490114, 2021). "A review of the literature found that six of the 12 upregulated genes (KPNA2, CDK1, TARBP1, PRC1, FEN1, and MCM6) were overexpressed in HCC tissue compared to levels in non-tumor tissue based on immunohistochemical staining." (PMID 32213663, 2020).
tumor (continued). "Taken together, these data indicate that CDK5RAP3 acts as a tumor suppressor by preventing the effects of MCM6." (PMID 31528213, 2019). "In progressive tumours, lower expression levels of MCM6 were observed, which is contrary to the Topo II α expression levels in our cohort." (PMID 31072339, 2019). "In cells, cell growth and invasiveness indicate that CDK5RAP3 acts as a tumor suppressor by preventing the effects of MCM6." (PMID 31528213, 2019). "In terms of histological grading, significantly less MCM6 expression levels were observed in higher differentiated tumours." (PMID 31072339, 2019). "Five genes namely ZWINT, CDC7, MCM4, MCM2 and MCM6 are proposed from the comprehensive computational analysis which gets affected in neoplasia stage and are responsible for the disease progression." (PMID 30150654, 2018). "Consistently, the liver orthotopic xenograft tumor also showed that MCM6 knockdown had imposed significant regulatory effects on HCC metastasis." (PMID 29357919, 2018). "Correlation analysis showed that MCM6 protein levels were significantly associated with Ki67 expression and differentiation, MCM7 with tumor size and Ki67 (P < 0.05)." (PMID 29463213, 2018). "Our results showed that mRNA levels of MCM2, MCM6 and MCM7 were associated with certain features of tumor and the outcomes of HCC patients." (PMID 29463213, 2018). "The results revealed that MCM6 expression in HCC tissues was markedly higher than the adjacent non-tumor liver tissue and normal liver tissue." (PMID 29357919, 2018). "Previous studies verified the important role of MCM6 in cell proliferation and indicated its potential role in prompting tumor progression." (PMID 29357919, 2018). "To further investigate the effects of MCM6 in vivo, we established subcutaneous xenograft tumor and orthotopic xenograft tumor models in nude mice." (PMID 29357919, 2018). "MCM6 functions as a tumor promotor by activating MEK/ERK signaling and subsequently regulates metastasis and EMT in HCC." (PMID 29357919, 2018). "MCM6, which we found to be up-regulated in tumor (0.328±0.283, median = 0.305, p = 0.0001) and in cell lines (0.387±0.178, median = 0.385, p = 0.0001) compared to normal (0.082±0.145, median = 0)." (PMID 23874974, 2013). "Kaempferol, which acted as a regulator of SIRT7, could enhance MCM6 Kcr level, alleviating tumour weight, especially combined with paclitaxel, which presents a potential chemotherapeutic target for BRCA therapy." (PMID 39477811, 2025). "Key genes such as MCM4, POLA1 and MCM6 are closely related to tumor immune invasion." (PMID 39083127, 2024). "Results showed that knockdown of MCM6 evidently suppressed the peritoneal dissemination as exemplified by fewer tumor nodules on the peritoneal surfaces in shMCM6 groups as compared with the control group, in agreement with the MCM6-induced epithelial-to-mesenchymal transition (EMT) phenomenon." (PMID 36185598, 2022). "We next asked whether inhibition of MCM6 by purpureaside C could also potentiate the anti-tumor effect of 5-FU in GC." (PMID 36185598, 2022). "Specifically, the inhibition of DBF4, CCNA2, CCNB1, MCM6, CDC45, CHEK1, and CDC6 may be implicated in KCNQ1-mediated tumor suppression." (PMID 35216393, 2022). "In addition, in vivo experiments further substantiated that overexpression of LINC00472 inhibited tumor growth and metastasis to lungs by decreasing the expression of MCM6." (PMID 33668040, 2021). "More and more evidence shows that MCM6 can predict tumor progression and prognosis." (PMID 34233647, 2021). "Moreover, the in vivo experiments also confirmed the important role of MCM6 in tumor genesis, and suggested that this effect is related to cell proliferation." (PMID 34233647, 2021). "The evidence suggests that the inhibitory effects of overexpressed LINC00472 are valid on tumor growth and metastasis to lungs in vivo, which could be induced by inhibition of MCM6." (PMID 33668040, 2021).